KRTAP12-4 (keratin associated protein 12-4)
Description:
In the hair cortex, hair keratin intermediate filaments are embedded in an interfilamentous matrix, consisting of hair keratin-associated proteins (KRTAP), which are essential for the formation of a rigid and resistant hair shaft through their extensive disulfide bond cross-linking with abundant cysteine residues of hair keratins. The matrix proteins include the high-sulfur and high-glycine-tyrosine keratins.
Synonyms: KRTAP12.4
Tractability: No criterion of Open Targets' tractability assessment is met for any kind of drug.
Gene: Protein-coding gene on chromosome 21 (44,654,213 to 44,654,659, reverse strand). Ensembl gene ENSG00000212933.
Pathways (Reactome):
Developmental Biology: Keratinization
Gene Ontology:
Molecular function: protein binding
Cellular component: cytosol
Genetic constraint (gnomAD): Loss-of-function variants: 1 observed, 0.52 expected, observed/expected ratio (o/e) 1.92, 90% interval 0.34 to 1.93. That is too few expected variants to judge how well the gene tolerates losing a copy. Missense variants: 148 observed, 142.88 expected, observed/expected ratio (o/e) 1.04, 90% interval 0.9 to 1.19. Synonymous variants: 58 observed, 59.53 expected, observed/expected ratio (o/e) 0.97, 90% interval 0.79 to 1.21.